SDHC (succinate dehydrogenase complex subunit C)
Diseases named in the same sentence as SDHC in open-access papers (continued):
Sharing a sentence is not in itself a finding about the gene and the disease.
gastrointestinal stromal tumor (18 papers, 2012 to 2025). "Paraganglionic tumors can also be found in association with gastrointestinal stromal tumors (GIST) and pulmonary chondromas in the so-called Carney triad, a nonhereditary condition characterized by epigenetic alterations of SDHC." (PMID 38108848, 2024). "For instance, gastrointestinal stromal tumors (GISTs) with succinate dehydrogenase (SDH) deficiency exhibit distinct hypermethylation patterns that distinguish them from classical GIST, and the silencing of SDHC via promoter hypermethylation has also been identified in certain GIST cases." (PMID 40427586, 2025). "It comprises four subunits (SDHA, SDHB, SDHC and SDHD), any of which may be targeted in a subset of gastrointestinal stromal tumors (GIST) leading to SDH deficiency." (PMID 33921435, 2021). "Heterozygous germline mutations in SDH complex (SDHx) genes (SDHA, SDHB, SDHC, SDHD, and SDHAF2), which act as tumor suppressor genes, predispose to pheochromocytomas and paragangliomas (PPGLs) and rarely to gastrointestinal stromal tumors (GIST), renal cell carcinoma, and pituitary adenomas." (PMID 35892689, 2022).
breast carcinoma (8 papers, 2009 to 2025). "On average, SDHC mutations are found in 1.5% of all cancers; the most common types are lung cancer, breast cancer, pancreatic cancer, colon cancer, and bladder cancer." (PMID 36251702, 2022). "We show that reduced expression of SDHC was particularly associated with EMT in the breast cancer cohorts of this study, especially the ductal- and basal-like subgroups." (PMID 31164982, 2019). "In summary, these data linked EMT to SDHC suppression in breast cancer and suggested that TWIST and SNAI2, two of the master promoters of EMT, could be involved." (PMID 31164982, 2019). "Interestingly, when looking at overall survival, low SDHC level was associated with a worse outcome in basal-like breast carcinoma." (PMID 31164982, 2019). "Furthermore, upon histological classification of the n = 204 breast cancer cohort, we found the inverse association between SDHC and EMT to be more pronounced in the ductal subgroup, compared to the lobular, but we did not see an impact on the overall survival." (PMID 31164982, 2019). "The downregulation of SDHC in breast cancer promotes epithelial to mesenchymal transition and reconstructs the structure of mitochondrial organelles." (PMID 33584825, 2021). "This study support that attenuation of SDH represents an inherent element and driver mechanism of the EMT program and especially points to SDHC as a contributing factor in the context of breast cancer." (PMID 31164982, 2019). "Thorough analyses in breast cancer patient cohorts revealed a relatively consistent inverse association between EMT and reduced expression of the SDHC subunit." (PMID 31164982, 2019). "Upon molecular and histological classification of the breast cancer cohorts, we found that the relationship between SDHC and EMT was stronger in the basal-like subgroup compared to the non-basal-like subgroup." (PMID 31164982, 2019). "Gene expression analysis suggested that there is a regulatory relationship between EMT-related genes and SDH subunits, especially regarding SDHC, in the breast cancer cohorts of this study." (PMID 31164982, 2019). "Our results suggest that SDHC expression could serve as a potential prognostic marker to enable further discrimination in the basal-like breast carcinoma subgroup." (PMID 31164982, 2019). "In basal breast cancer cases with a high WWOX/HIF1A ratio, pathways favouring oxidative phosphorylation (Complexes I–V: NDUFA/B/C/S/V, SDHC, COX, ATP6 family) were enriched, reducing reliance on glycolysis and limiting tumour proliferation." (PMID 41007296, 2025). "To explore the impact of reduced SDHC expression on EMT-related features, we knocked down this gene in MCF7 breast cancer cells, using the CRISPR/Cas9 system." (PMID 31164982, 2019). "Correlation analysis was performed to evaluate the relationship between SDHC expression and EMT status within each breast cancer subgroup." (PMID 31164982, 2019). "Since HIF-1α is frequently expressed in breast carcinomas, DNA methylation at the promoter regions of the SDHA, SDHB, SDHC and SDHD and FH genes was evaluated as a possible mechanism in silencing of SDH and FH expression in breast carcinomas." (PMID 19778456, 2009). "Furthermore, a feed‐forward loop initiated by SDHC knock‐out in breast cancer cells mediated enhanced TWIST1 and SNAI1 expression favoring SDHC suppression and reduction of SDH complex activity." (PMID 37899663, 2024). "Although the expression level of SDHC was not significantly downregulated in the breast cancer tissues, the trend of SDHC expression was consistent with that of RWDD4, SEPT7, and SFN expression." (PMID 32156290, 2020). "No DNA methylation was identified in the promoter regions of the SDHA, SDHB, SDHC, SDHD and FH genes in 72 breast carcinomas and 10 breast cancer cell lines using methylation-sensitive high resolution melting which detects both homogeneous and heterogeneous methylation." (PMID 19778456, 2009).
breast carcinoma (continued). "In conclusion, promoter methylation of the SDHA, SDHB, SDHC, SDHD and FH genes is unlikely to be an important mechanism in stabilising HIF-1 in breast carcinomas through the downregulation of the expression of SDH and FH genes." (PMID 19778456, 2009).
Carney-Stratakis syndrome (7 papers, 2014 to 2025). Carney-Stratakis syndrome is a recently described familial syndrome characterized by gastrointestinal stromal tumors (GIST) and paragangliomas, often at multiple sites. "Most of SDH mutations in GIST are germline, in particular germline mutations in SDHB, SDHC, and SDHD occur in about 20–30% of SDH-deficient disease and may be referred to as a Carney-Stratakis syndrome (CSS)." (PMID 35059314, 2021).
head and neck paraganglioma (7 papers, 2006 to 2024). A benign or malignant extra-adrenal paraganglioma arising from paraganglia in the head and neck. "In this study we detected germline mutations of SDHB in 5% and of SDHC in 2.5% of sporadic head and neck paraganglioma cases." (PMID 16405730, 2006). "Of the sporadic head and neck paraganglioma cases 8% were found to carry a germline mutation of SDHB or SDHC." (PMID 16405730, 2006). "Although relatively few SDHC mutations carriers are known, totaling 15 individuals, including 4 with no other known affected family members, all affected individuals had head and neck paragangliomas, including one case of a metastatic, catecholamine-secreting carotid body tumor." (PMID 16405730, 2006). "Including our previous results, we have screened a total of 95 sporadic head and neck paraganglioma cases for germline mutations of SDH genes and found 24 (25%) in SDHD, 2 (2%) in SDHB and 1 (1%) in SDHC (total = 28%)." (PMID 16405730, 2006). "An even rarer cause for head-and-neck paraganglioma is the SDHAF2 mutation, which should be considered if SDHD, SDHB, and SDHC testing is negative." (PMID 29166454, 2017).
metastatic disease (7 papers, 2018 to 2026). "Meta-analyses have also been conducted in the other SDH variants, revealing the metastatic disease prevalence of 23% to 31% for SDHB, 23% for SDHC, 16% for SDHA, and 6% to 8% for SDHD." (PMID 41183483, 2026). "We cultured 62 PPGLs, including tumours with confirmed SDHB, SDHC and SDHD variants, as well as several metastatic tumours." (PMID 36178902, 2022). "In total, 18 patients suffered from metastatic disease; germline mutations in SDHA, SDHB and SDHC were present in one patient each, while SDHD mutations were found in seven patients." (PMID 35171114, 2022). "Metastatic disease is one of the features that indicates likelihood of a hereditary cause, and it is recommended that patients with malignant PCC should undergo genetic testing for SDHB, SDHC, SDHD, VHL and MAX." (PMID 29768630, 2018). "In our analyses of risk rate not adjusted for time, we found a significantly increased risk of metastatic disease in patients with pathogenic germline variants in SDHA, SDHB, SDHC, TMEM127, MAX, and FH compared to those with no identified pathogenic variant." (PMID 41183483, 2026).
renal cell carcinoma (7 papers, 2019 to 2025). "Germline mutations within the Krebs cycle enzyme genes fumarate hydratase (FH) or succinate dehydrogenase (SDHB, SDHC, SDHD) are associated with an increased risk of aggressive and early metastasizing variants of renal cell carcinoma (RCC)." (PMID 36455002, 2022). "Patients with dSDH wtGIST due to a germline variant in SDHx or SDHC epimutations are at risk of multiple tumours including multifocal PPGL, pulmonary chondroma and renal cell carcinoma." (PMID 33443647, 2021). "Mutations in protein subunits of succinate dehydrogenase (SDHA/SDHB/SDHC/SDHD and assembly factor SDHAF2) and fumarate hydratase (encoded by the single gene FH) lead to rare forms of renal cell carcinoma (RCC; denoted by SDHRCC and FHRCC, respectively)." (PMID 35288096, 2022).
von Hippel-Lindau disease (6 papers, 2005 to 2024). An autosomal dominant disorder caused by pathogenic variants in the VHL gene, leading to an increased risk of various benign and malignant tumors, including hemangioblastomas, retinal hemangiomas, endolymphatic sac tumors, renal cell carcinoma, and pheochromocytomas. "Due to histopathologic diagnosis, genetic testing for familial paraganglioma, neurofibromatosis type 1, von Hippel-Lindau disease, the Carney triad, multiple endocrine neoplasia type 2, and mutations of the succinate dehydrogenase genes (SDHB, SDHC, and SDHD) was performed that was negative." (PMID 17683569, 2007).
multiple endocrine neoplasia (4 papers, 2018 to 2023). Multiple endocrine neoplasia (MEN) is a group of rare inherited cancer syndromes characterized by the development of two or more endocrine gland tumors, sometimes with tumor development in other tissues or organs. "Examples of PPGLA mutations include the RET gene in multiple endocrine neoplasia (MEN) syndromes, the VHL gene in von Hippel–Lindau disease, the NF1 gene in Neurofibromatosis type 1, the MAX gene, or the genes of the succinate dehydrogenase complex (SDHB, SDHD, SDHA, SDHC, SDHAF2)." (PMID 36010170, 2022).
renal carcinoma (4 papers, 2021 to 2025). A carcinoma arising from the epithelium of the renal parenchyma or the renal pelvis. "In addition, germline loss-of-function mutations of the TCA cycle enzyme genes, including FH, SDHB, SDHC, and SDHD, have been identified in renal cancers that appear to have an increased risk for more aggressive tumors." (PMID 34609963, 2021).
acute myeloid leukemia (3 papers, 2021 to 2025). Acute myeloid leukemia (AML) is a group of neoplasms arising from precursor cells committed to the myeloid cell-line differentiation. "Abnormal levels of GATA-1S and SDHC variants were also found in an acute myeloid leukemia patient, thus supporting in vitro results." (PMID 34679737, 2021). "Herein, we report a 5-year-old girl carrying a VUS in the Succinate Dehydrogenase Complex Subunit C (SHDC) gene who had been previously treated for high-risk neuroblastoma and subsequently followed by the development of secondary acute myeloid leukemia." (PMID 38260858, 2024).
colon carcinoma (3 papers, 2021 to 2023). "According to the PDC database, compared with normal tissues, SDHA (p < 2.2×10-16), SDHB (p = 1.1×10-13), SDHC (p = 1.2 ×10-10), and SDHD (p = 0.00028) were low expressed in colon cancer at protein level." (PMID 36949947, 2023). "Interestingly, in the colon carcinoma cell line HCT116 where there is a significant reduction in growth in hypoxia, knockdown of SDHC did not improve proliferation in hypoxia, and instead significantly reduced cell growth in hypoxia." (PMID 34021238, 2021).
colorectal cancer (3 papers, 2015 to 2024). A primary or metastatic malignant neoplasm that affects the colon or rectum. "Studies on the association of SNPs in the SDHC gene were conducted for the prognosis of patients with colorectal cancer." (PMID 33053772, 2020). "To further investigate the expression of SDHC in colorectal cancer, we analyzed GES128435 and GSE64857." (PMID 38844980, 2024). "Online database were utilized to investigate the expression of SDHC in colorectal cancer and to assess its correlation with patient prognosis." (PMID 38844980, 2024). "The results from UALCAN indicate that mRNA levels and protein levels of SDHC are downregulated in colorectal cancer." (PMID 38844980, 2024). "Moreover, when compared to normal intestinal epithelial cells, various colorectal cancer cell lines exhibited low expression of SDHC at both mRNA and protein levels." (PMID 38844980, 2024). "As a subunit of SDH, succinate dehydrogenase complex subunit C (SDHC) has been revealed to play tumor suppressive roles in several cancers, while its specific role in colorectal cancer (CRC) still needs further investigation." (PMID 38844980, 2024). "However, there have been no studies reporting the role of SDHC in colorectal cancer, and its specific mechanism of action needs to be elucidated." (PMID 38844980, 2024).
hepatocellular carcinoma (3 papers, 2021 to 2022). A malignant tumor that arises from hepatocytes. "As one of the lines of evidence, downregulation of SDHC expression resulted in decreased mitochondrial SDH activity and increased ROS levels in hepatocellular carcinoma (HCC) cells, thereby promoting HCC cell growth and metastasis in vitro and in vivo." (PMID 35530337, 2022).
ovarian carcinoma (3 papers, 2022 to 2025). A malignant neoplasm originating from the surface ovarian epithelium. "Multiple types of mutations in SDHC have been observed in ovarian cancer and pancreatic cancer." (PMID 36251702, 2022).
Carney triad (2 papers, 2021 to 2024). Carney's triad is a rare non-hereditary condition characterized by gastrointestinal stromal tumors (GIST, intramural mesenchymal tumors of the gastrointestinal tract with neuronal or neural crest cell origin), pulmonary chondromas and extraadrenal paragangliomas. "The epigenetic inactivation of the SDHC gene locus may be the cause of tumorigenesis in patients with Carney triad (CT)." (PMID 33584825, 2021). "The cause of CT (Carney triad) is not yet clear, but recent studies suggest an involvement of the Succinate dehydrogenase complex subunit C (SDHC) gene." (PMID 39334573, 2024).
glioma (2 papers, 2019 to 2022). A benign or malignant brain and spinal cord tumor that arises from glial cells (astrocytes, oligodendrocytes, ependymal cells). "Firstly we undertook SDHC promoter methylation analysis on 17 IDH1 mutant glioma samples." (PMID 31308404, 2019). "The mean SDHC promoter methylation in the IDH1 mutant glioma samples was 2% (±SD 1.28, range 1–4%)." (PMID 31308404, 2019).
leukemia (2 papers, 2021 to 2022). A malignant (clonal) hematologic disorder, involving hematopoietic stem cells and characterized by the presence of primitive or atypical myeloid or lymphoid cells in the bone marrow and the blood. "Moreover, another aspect that needs to be considered is the relevant contribution of dysregulated alternative splicing mechanisms underlying both GATA-1S and SDHC ASVs expression in promoting leukemia development." (PMID 34679737, 2021). "Although it is currently unknown if GATA-1S has a direct role in the alteration of the splicing machinery, our results clearly indicate that, along with unbalanced GATA-1 isoform ratio, aberrant expression of SDHC ASVs emerges as a leukemia-promoting factor." (PMID 34679737, 2021). "SISU-102 clearly inhibited the expression of the HSF1 targets, HSP90 and SDHC, and HSF1 itself, in a dose-dependent manner and strongly suppressed the growth and OCRs of murine MLL-AF9 Hsf1fl/flcreER leukemia cells and human MV4–11 and NOMO-1 AML cells." (PMID 36245043, 2022).
neuroblastoma (2 papers, 2019 to 2024). Neuroblastoma (NB) is the most common solid, extracranial childhood tumor. "We report that SDHC-loss MEFs display an attenuated cell death response to retinoic acid and that SDH-inhibited SH-SY5Y neuroblastoma cells display attenuated retinoic acid-induced neuronal differentiation." (PMID 31234811, 2019).
neurofibromatosis (2 papers, 2020 to 2022). A hereditary neoplastic syndrome in which tumors grow in the nervous system. "Two nonsyndromic patients (cases 1 and 2) were negative to germline mutations in genes VHL, SDHB, SDHC, SDHD, SDHAF2, TMEM127, and MAX, while the third case (case 3) had clinical diagnosis of neurofibromatosis syndrome." (PMID 36187102, 2022).
Obesity (2 papers, 2022 to 2024). Accumulation of substantial excess body fat. "We hypothesized that this phenotype results from the deletion or altered behavior of SDHC‐loss TH+ cells important for dopamine signaling in feeding behavior and obesity." (PMID 39399478, 2024). "Surprisingly, SDHC loss in TH+ cells caused an obesity phenotype starting at 20 weeks of age." (PMID 39399478, 2024). "The loss of SDHC in TH+ glomus cells leads to increased obesity in a mouse model." (PMID 36291149, 2022).
pheochromocytoma and paraganglioma (2 papers, 2017 to 2021). "The majority of hereditary pheochromocytoma and paraganglioma (PPGL) is caused by germline mutations in the SDHB, SDHC, or SDHD genes, which encode three (SDHB, SDHC, SDHD) of five subunits of succinate dehydrogenase (SDH) enzyme (SDHA, SDHDB, SDHC, SDHD, SDHAF2)." (PMID 34356532, 2021).
tuberous sclerosis (2 papers, 2023 to 2025). Hereditary disease characterized by seizures, intellectual disability, developmental delay, and skin and ocular lesions.
-deficient (1 paper, 2018). "Succinate dehydrogenase-deficient RCC is rare and results from inherited germline mutations in the succinate dehydrogenase (SDH) gene, most commonly SDHB but also in SDHA, SDHC and SDHD." (PMID 30123932, 2018).
breast tumors (1 paper, 2019). "We found an overall inverse association between EMT and the SDH subunit C (SDHC) when analyzing gene expression in breast tumors." (PMID 31164982, 2019). "The initial gene expression analysis in human breast tumors and cell lines convincingly suggested that EMT is associated with reduced SDHC expression." (PMID 31164982, 2019).